IL18 (interleukin 18)
Diseases named in the same sentence as IL18 in open-access papers (continued):
Sharing a sentence is not in itself a finding about the gene and the disease.
asthma (continued). "IL-18 protects against RV-induced colds and asthma exacerbations and plays an important role in the early antibacterial host response during pneumococcal pneumonia and Streptococcus agalactiae infection." (PMID 39431236, 2024). "For instance, an increase in serum IL-18 levels was documented with a decrease in FEV1 in the patients with asthma-COPD-overlap." (PMID 39554494, 2024). "ELISA was used to measure concentrations of cytokines (IL-1β, IL-18, IL-17A, and IL-10) in serum samples collected from asthma patients and healthy individuals." (PMID 38849380, 2024). "IL-18 levels were higher in patients with acute asthmaIL-18 levels were higher during acute asthma exacerbation than on remission days.IL-18 level had a tendency to inversely correlate with peak expiratory flow." (PMID 39554494, 2024). "In recent years, research has confirmed the significant role of IL-18 in the pathogenesis of asthma." (PMID 38162651, 2023). "The stimulatory ability of IL-18 regarding leukocytes allows it to participate in various allergic responses, including rhinitis, dermatitis, asthma, and eosinophilic disorders." (PMID 38003107, 2023). "We identified HMOX1, ITGAM, SFTPD and ADAM17 as the top novel targets for asthma which need to be validated experimentally whereas IL-18, TNF and VEGFA as the strongest therapeutic targets to investigate further for clinical benefit." (PMID 37735578, 2023). "Through our analysis, we have identified that IL-18 plays a significant role in the pathway from asthma to UC." (PMID 38162651, 2023). "Secondly, the investigation concerning asthma,IL-18 and UC relies on individuals of European descent." (PMID 38162651, 2023). "TNF, VEGFA and IL-18 were the other top targets identified to be explored for therapeutic benefit in asthma but need further clinical testing." (PMID 37735578, 2023). "NLRP3 and IL-18 protein levels of airway epithelial cells in lung biopsies of patients with asthma were found higher than those of healthy people." (PMID 36248872, 2022). "Induced total sputum IL‐18, IL‐18BP and calculated free IL‐18 levels were detected both in patients with asthma and in healthy controls." (PMID 34194747, 2021). "On the other hand, reduced levels of IL-18 were found in the bronchoalveolar lavage (BAL) fluid of patients with asthma compared with healthy controls." (PMID 33378691, 2021). "The expression of IL‐18, IL‐18BP and IL‐18Rα was examined in subjects with asthma and healthy controls in bronchial biopsies by immunohistochemistry and IL‐18 and IL‐18BP release in sputum." (PMID 34194747, 2021). "In sputum, IL‐18BP was increased in stable asthma with a non‐significant decrease in free IL‐18 in sputum in asthma compared with healthy controls." (PMID 34194747, 2021). "The IL‐18 epithelial reciprocal intensity staining was decreased in subjects with asthma compared with healthy controls (P = 0.039)." (PMID 34194747, 2021). "IL-18 was induced following acute Aspergillus challenge and during a chronic model of fungal-sensitized asthma." (PMID 33643264, 2021). "In this study, we demonstrated that the expression of IL‐18 was significantly lower in bronchial epithelium in subjects with asthma than in healthy controls." (PMID 34194747, 2021). "We validated IL18R1 protein expression in lung tissue and identified downstream NF-κB and AP-1 activity, supporting IL-18 signaling in severe asthma pathogenesis and highlighting this approach for gene and pathway discovery." (PMID 34591794, 2021). "In conclusion, in asthma the interactions between IL‐18, its receptor and its natural inhibitor IL‐18BP are complex with differences between airway compartments." (PMID 34194747, 2021). "In subjects with stable asthma, the expression of IL‐18 was decreased compared with healthy controls." (PMID 34194747, 2021). "In asthma, the dynamic interaction between IL‐18, its cognate receptor and natural inhibitor is complex with differences between airway compartments." (PMID 34194747, 2021).
asthma (continued). "In cases of fatal asthma, post‐mortem biopsies have shown increased levels of IL‐18 in the epithelium and ASM, compared with control samples." (PMID 34194747, 2021). "It has been described that airway epithelial cells were induced to release IL-18 in other disease conditions such as asthma." (PMID 35111152, 2021). "Exposure to gastric bacteria H. pylori can also drive asthma protection by inducing IL-18 in dendritic cells through the NLRP3/CASP1/IL-18 axis." (PMID 33546184, 2021). "The IL-18/IL-12 serum ratio in vivo was also significantly higher in patients with both diseases compared to those with only asthma." (PMID 34071190, 2021). "Due to its Th-2-inducing functions, IL-18 can also participate in inflammation and hyperreactivity of the respiratory tract in asthma and promote the recruitment of eosinophils to the airways." (PMID 32733164, 2020). "Little is known about expression of IL‐18, IL‐18BP and IL‐18R in peripheral blood B cells, and we therefore examined expression of them in B cells of asthma patients." (PMID 28922563, 2018). "A 13‐fold (95%/7.3%) more monocytes, 17.5‐fold (70%/4%) more neutrophils and 4.1‐fold (69.3%/17%) more B cells express IL‐18BP than IL‐18 indicate that there is excessive amount of IL‐18BP to completely abolish actions of IL‐18 in asthma." (PMID 28922563, 2018). "As a wide range of other cell types also expresses IL‐18R 8, it is very likely that huge number of IL‐18R expressing inflammatory cells is ready to react to IL‐18 in patients with asthma, suggesting the importance of IL‐18R in asthma." (PMID 28922563, 2018). "It has been reported that human neutrophil can release IL‐18 14, which can be a source of enhanced plasma IL‐18 of asthma patients." (PMID 28922563, 2018). "Little is known about the sources of increased plasma level of IL‐18 and expression level of IL‐18R on inflammatory cells in asthma." (PMID 28922563, 2018). "Because monocytes/macrophages, neutrophils and B cells are involved in the pathogenesis of asthma, and they have close relationship with IL‐18, we first examined expression of IL‐18, IL‐18BP and IL‐18R in these cells." (PMID 28922563, 2018). "It was observed that IL‐18 and IL‐18BP were correlated well with each other in the plasma of patients with asthma and HC volunteers." (PMID 28922563, 2018). "We demonstrated that 13‐fold more monocytes, 17.5‐fold more neutrophils and 4.1‐fold more B cells express IL‐18BP than IL‐18 in asthmatic blood, suggesting that there is excessive amount of IL‐18BP to abolish actions of IL‐18 in asthma." (PMID 28922563, 2018). "We therefore examined expression of IL‐18, IL‐18BP and IL‐18R in parallel in inflammatory cells of asthma." (PMID 28922563, 2018). "We therefore believe that actions of IL‐18 in asthma depend on the balance between IL‐18 and IL‐18BP." (PMID 28922563, 2018). "To further understand the involvement of IL‐18 in asthma, we examined expression of IL‐18, IL‐18BP and IL‐18R in peripheral blood neutrophils." (PMID 28922563, 2018). "Using ELISA kits, we observed that levels of IL‐18 were 270.7 and 169.0 pg/ml, and levels of IL‐18BP were 3460 and 1910 pg/ml in the plasma of patients with asthma and HC volunteers, respectively." (PMID 28922563, 2018). "Our data clearly indicate that the role of IL‐18 in asthma is very likely to be determined by balance of IL‐18/IL‐18BP/IL‐18R expression in inflammatory cells." (PMID 28922563, 2018). "It is recognized that IL‐18 is related to development of asthma, but role of IL‐18 in asthma remains controversial and confusing." (PMID 28922563, 2018). "In summary, the correlation between IL-18 and tryptase in plasma of patients with asthma indicates close interactions between them, which should be considered for development of anti-IL-18 and antitryptase therapies." (PMID 27069315, 2016).
asthma (continued). "Using flow cytometric analysis technique and ovalbumin- (OVA-) sensitized mouse model, it was found that IL-18 and tryptase levels in the plasma of moderate and severe asthma were elevated, and they correlated well with each other." (PMID 27069315, 2016). "Since IL-18 and tryptase alone have been observed to play key roles in asthma and their plasma levels correlated well in asthma, there must be some close interactions between them." (PMID 27069315, 2016). "From our data, it seems that serum IL-18 is underexpressed in childhood asthma probably because of consumption at an early stage of asthma pathogenesis." (PMID 23283012, 2009). "Wider scale studies are indicated to verify the alterations in IL-18 levels according to the different protocols of asthma therapy." (PMID 23283012, 2009). "Serum IL-18 levels during asthma exacerbations ranged from 65 to 200 pg/mL [median = 125 pg/mL; mean (SD) = 128.6 (43.3) pg/mL]." (PMID 23283012, 2009). "In contrast, a study of 370 schoolchildren aged 9 to 10 years living in urban Japanese areas revealed that serum IL-18 levels were significantly higher in children who had asthma, allergic rhinitis, or atopic eczema than in the rest of the enrolled children." (PMID 23283012, 2009). "Vaccination with allergen-IL-18 fusion DNA protects against, and reverses established, airway hyperresponsiveness in an animal model of asthma." (PMID 18315837, 2008). "Decreased expression of immuno-regulatory cytokines, including IL-12, IL-18, or interferon gamma, can strengthen the inflammatory process and play regulatory roles in asthma by modifying Th2 lymphocyte responses." (PMID 16083514, 2005). "Importantly, before anti-IL-18 therapeutics are considered for treating severe asthma, further studies are needed to characterize the in vivo phenotype and effect of IL-18/IL-18R signaling on ILC2 activation in asthma models." (PMID 40777291, 2025). "Considering the pathogenic role that IL-17A-producing ST2+ cells may play in refractory asthma, future studies will need to better clarify the role of IL-18 in the regulation of this IL-17A+ ST2+ ILC2 population." (PMID 40777291, 2025). "Moreover, the gene expression of IL‐18 (IL18) was higher after infection in patients with asthma compared to healthy individuals, in line with inflammasome activation." (PMID 39466641, 2025). "Elevated airway IL-17A levels are linked to neutrophilia in asthma, though the precise role of IL-17A in asthma or how IL-17A is regulated by IL-18 are not well characterized." (PMID 40777291, 2025). "This pathway contributes to both the development and exacerbation of asthma by mediating the release of pro-inflammatory cytokines such as IL1β and IL18, which are critical in the pathogenesis of severe steroid-resistant asthma (SSRA) and other asthma phenotypes." (PMID 40598285, 2025). "Summary of clinical studies about IL-18 and asthma in animal models." (PMID 39554494, 2024). "Numerous studies implicate NLRP3 inflammasomes, IL-1β and IL-18 in the development of asthma." (PMID 39131161, 2024). "Additionally, IL-18’s involvement in autoimmune processes introduces a new dimension to understanding severe asthma, particularly in cases where traditional therapies targeting Th2 inflammation have shown limited effectiveness." (PMID 39554494, 2024). "Even though IL-18 is not recognized to be a major player in asthma pathobiology, several recent studies have linked IL-18 to diverse immune responses in asthma." (PMID 39554494, 2024). "Therefore, IL-18 can orchestrate chronic inflammation in severe asthma beyond the canonical T2 pathways." (PMID 39554494, 2024). "N-GSDMD, IL-18, and IL-1β were significantly increased in asthma group." (PMID 39554494, 2024). "Importantly, emerging evidence highlights IL-18 as a critical player in severe asthma, contributing to chronic airway inflammation, airway hyperresponsiveness (AHR), and mucus impaction." (PMID 39554494, 2024).
asthma (continued). "Furthermore, we discuss the emerging evidence of IL-18’s involvement in autoimmunity and highlight potential therapeutic targets within the IL-18 and inflammasome pathways in severe asthma patients with evidence of infections and airway autoimmune responses." (PMID 39554494, 2024). "Through pore formation in the cell membrane and release of the proinflammatory cytokines IL (interleukin)-1β and IL-18, pyroptosis not only eliminates harmful microbes from the body but also aggravates inflammatory conditions including respiratory diseases such as asthma or COPD." (PMID 39336475, 2024). "Additionally, we performed sensitivity analyses for two sets of MR studies, namely, the relationships between asthma and UC, and asthma and IL-18." (PMID 38162651, 2023). "For asthma patients, controlling the disease and monitoring IL-18 levels can contribute to disease prevention and early detection and may also reduce the risk of developing UC." (PMID 38162651, 2023). "A recent study found that IL-18R was highly expressed in the lung of the most severe asthma patient cluster, supporting that IL-18 signaling may play a key role in the pathogenesis of severe asthma." (PMID 35807067, 2022). "Taken together these data provide evidence for an NLRP1 dependent IL18-mediated protective role in asthma, that could be disrupted by an altered NLRP1 activation related to polymorphisms such as rs11651270/C." (PMID 36189256, 2022). "Similarly, high serum IL-18 levels have been found in patients with uncontrolled asthma and in mild and moderate asthma exacerbations." (PMID 35807067, 2022). "In asthma, the interplay between IL‐18, IL‐18BP and IL‐18R20, 21 is poorly understood and whether the IL‐18 axis impacts epithelial repair or EMT‐associated cell protein or gene expression is unknown." (PMID 34194747, 2021). "This perhaps suggests that IL‐18 might play a key role following airway infection whilst at lower levels during stable asthma." (PMID 34194747, 2021). "To test our hypothesis, we investigated IL‐18, IL‐18BP and IL‐18Rα expression in bronchial biopsies and quantified sputum cytokine release in asthma and healthy controls." (PMID 34194747, 2021). "This possible dynamic role for IL‐18 in the pathogenesis of asthma warrants further investigation." (PMID 34194747, 2021). "Moreover, significantly increased serum levels of IL-18 were found in patients during acute asthma episodes." (PMID 33378691, 2021). "IL‐18 was released in sputum with IL‐18BP elevated in patients with asthma." (PMID 34194747, 2021). "IL-18 may promote type I inflammation via immune cell production of IFN-γ, which has been previously implicated in CS-resistant asthma." (PMID 34591794, 2021). "Therefore, we wanted to further investigate the role of the proinflammatory cytokines IL-1β and IL-18 in mediating protection during asthma, because both cytokines are released on Nlrp1 activation." (PMID 33378691, 2021). "Taken together, these findings support our hypothesis that IL‐18 might promote airway remodelling in asthma via effects on epithelial repair, induction of cellular differentiation and EMT protein expression changes." (PMID 34194747, 2021). "Importantly, in earlier reports IL‐18 in blood and sputum was found to be increased markedly during asthma exacerbations." (PMID 34194747, 2021). "If we were to use fresh bronchial brushes for all the studies and allowed the epithelial cells to fully differentiate to ALI cultures, this may have been a robust way of investigating IL‐18 in relation to asthma." (PMID 34194747, 2021). "IL‐18 is increased in sputum and blood samples during asthma exacerbations." (PMID 34194747, 2021). "IL-18 pathway components are increased in the most severe asthma patients." (PMID 34591794, 2021). "IL-18 also has autoimmune regulatory effects on both Th1 and Th2 cytokines and several studies have demonstrated increase in IL-18 activity in Th2 type diseases, such as asthma exacerbations and allergic rhinitis." (PMID 32448302, 2020).
asthma (continued). "However, there were still controversial researches showing that sputum supernatants and serum IL-18 were found at low levels in patients with severe refractory asthma (SRA)." (PMID 30373775, 2019). "As IL‐18 stimulates T cells to produce increased IFN‐γ, IL‐13 and IL‐5 23, and IL‐13 and IL‐5 are potent Th2 cytokines, which play key pro‐inflammatory role in atopic asthma, it is believed that IL‐18 ought to be a causative factor for asthma." (PMID 28922563, 2018). "However, a study demonstrated that activation of the TLR2/NLRP3/IL‐18 axis can protect against asthma 3, complicating the role of IL‐18 in asthma." (PMID 28922563, 2018). "In this study, we found that plasma levels of IL‐18 and IL‐18BP were elevated in asthma." (PMID 28922563, 2018). "Moreover, the finding that sensitization reduced number of IL‐18R+ macrophages in lung further decreases the capability for IL‐18 contributing to development of asthma." (PMID 28922563, 2018). "However, little is known about influence of allergens on expression of IL‐18, IL‐18BP and IL‐18R in asthma." (PMID 28922563, 2018). "However, DAE seemed to induce elevated MFI of IL‐18 and IL‐18BP (Fig. 4Gii and I) in B cells of asthma patients." (PMID 28922563, 2018). "The ratio between plasma concentrations of IL‐18 and IL‐18BP was 1:12.8 in asthma patients." (PMID 28922563, 2018). "An imbalance between IL‐18 and IL‐18BP expression may account for increased IL‐18 activity in asthma." (PMID 28922563, 2018). "It was noticed that IL-18 significantly correlated with tryptase in asthma." (PMID 27069315, 2016). "The inhibitory effect was through regulating IL-18 activity and thus may be candidate of therapeutic target for IL-18-initiated diseases, including MS, RA, and asthma." (PMID 25050341, 2014). "It has been suggested that IL-18 may play an important role in the pathophysiology of patients with asthma." (PMID 23382928, 2013). "In addition, significantly higher serum IL-18 levels have been reported in patients with acute severe asthma." (PMID 23382928, 2013). "We hypothesized that overexpression of mature IL-18 protein in the lungs may exacerbate disease activities of asthma." (PMID 23382928, 2013). "Our results suggest that Alternaria exposure damages the airway epithelium and releases IL-18, and this release may be one of the mechanisms of initiation of asthma." (PMID 22347372, 2012). "Serum IL-18 levels during asthma exacerbation [median = 125 pg/mL; mean (SD) = 128.6 (43.3) pg/mL] were significantly lower than the follow-up levels during stability [median = 250 pg/mL; mean (SD) = 291.6 (66.7) pg/mL] and both levels correlated positively with each other." (PMID 23283012, 2009). "It was suggested that antioxidants may reduce IL-18 expression in asthma by inhibiting the activity of NF-Κb." (PMID 23283012, 2009). "The authors, however, stated that the effect of corticosteroids on IL-18 is currently uncertain because the sample with the highest level of IL-18 in their series came from a patient with asthma who was receiving 7 mg of prednisolone continuously (in addition to 800 μg/day of inhaled budesonide)." (PMID 23283012, 2009). "The same dualism is present in vivo after administration of IL-18 in animal models of asthma." (PMID 18315837, 2008). "This suggests that IL-18 may contribute to the development and exacerbation of Th2-mediated airway inflammation in asthma." (PMID 18315837, 2008). "Furthermore, given the elevated IL‐18 levels in asthma as well, future research should investigate whether IL‐18 promotes eosinophil differentiation and migration through distinct pathways in asthma versus COPD and EoE." (PMID 40492692, 2025). "While the mechanisms behind the regulatory roles of IL-18 in asthma continue to be characterized, further investigations into the regulation of ILC plasticity may provide insight into asthma pathogenesis and the implications of targeting IL-18R to treat this disease." (PMID 40777291, 2025).